MIR6770-3 (microRNA 6770-3)
Synonyms: hsa-mir-6770-3
Gene: MicroRNA gene on chromosome 16 (18,379,351 to 18,379,410, reverse strand). Ensembl gene ENSG00000275391.
Homologues: Paralogues in human: MIR6770-1 (100% identical), MIR6770-2 (100% identical).